MIR5590 (microRNA 5590)
Synonyms: hsa-mir-5590
Gene: MicroRNA gene on chromosome 2 (134,857,820 to 134,857,873, forward strand). Ensembl gene ENSG00000263783.
Homologues: Orthologues: chimpanzee MIR5590 (100% identical).